FLCN (folliculin)
Diseases named in the same sentence as FLCN in open-access papers (continued):
Sharing a sentence is not in itself a finding about the gene and the disease.
thyroid nodule (1 paper, 2025). A small circumscribed mass in the THYROID GLAND that can be of neoplastic growth or non-neoplastic abnormality. "Thyroid nodules have also been reported in patients with Birt–Hogg–Dubé (BHD) syndrome, an autosomal dominant condition caused by a germline folliculin (FLCN) mutation." (PMID 40277780, 2025). "However, published details regarding both germline and somatic FLCN alterations in thyroid nodules remain sparse." (PMID 40277780, 2025).
thyroid tumor (1 paper, 2025). A benign or malignant neoplasm affecting the thyroid gland. "Despite these insights, the role of FLCN in thyroid neoplasms remains largely unexplored, with only a few isolated reports linking FLCN mutations to thyroid tumors." (PMID 40277780, 2025). "Furthermore, review of additional FLCN-mutated thyroid tumors is essential for further characterization." (PMID 40277780, 2025). "Only two of these reports of thyroid tumors were examined genetically to confirm an FLCN alteration." (PMID 40277780, 2025). "As a result, it makes sense to include these cases in our evaluation of FLCN-altered thyroid tumors." (PMID 40277780, 2025). "To further underscore the importance of the inclusion of the FLCN gene in these assays, we are likely underestimating the number of thyroid tumors with FLCN alterations." (PMID 40277780, 2025). "Broadening genetic panels to include FLCN could improve the detection and characterization of FLCN-altered thyroid tumors." (PMID 40277780, 2025). "In this report, we describe two rare thyroid tumors with pathogenic FLCN alterations: one harboring a germline (heriditary) FLCN mutation in a patient with BHD syndrome and the other with a somatic (acquired) FLCN mutation." (PMID 40277780, 2025). "Until this study, however, there have been only isolated reports of thyroid tumors in patients with BHD, and no studies to date have documented somatic FLCN alterations in thyroid tumors." (PMID 40277780, 2025).
uterine cancer (1 paper, 2025). Primary or metastatic malignant neoplasm involving the uterine corpus and/or the cervix. "The patient with uterine cancer also had FLCN, MEN1 and NF1 PGVs, though none of these three PGVs are typically associated with the uterine carcinoma phenotype either." (PMID 41465149, 2025).
viral infection (1 paper, 2025). "The increase in FLCN transcriptional levels alongside the decrease in protein levels appears to reflect a competitive interplay between viral infection and the host cell." (PMID 40449101, 2025). "Simultaneously, we observed that the energy levels in FLCNOE cells post-viral infection were significantly lower compared to both WT and FLCN-/- groups." (PMID 40449101, 2025). "To further investigate this discrepancy, we analyzed the protein levels of FLCN following viral infection." (PMID 40449101, 2025).
tumor (132 papers, 2008 to 2026). "All FLCN‐mutated tumours, including the sporadic ones and those with somatic FLCN mutations, appear to consistently and diffusely express GPNMB on IHC, which is reflective of the underlying mTORC1 dysregulation, leading to TFEB activation." (PMID 41384711, 2026). "FLCN‐mutated tumours in BHD are also different from the sporadic ChRCC, and exhibit completely different expression profiles, as well as nuclear and mitochondrial DNA signatures." (PMID 41384711, 2026). "The FLCN gene encodes the folliculin protein, a tumor suppressor involved in key cellular signaling pathways, including the mTOR pathway, which plays a role in cellular growth, differentiation, and metabolism." (PMID 40575199, 2025). "This condition is widely believed to be associated with mutations in the FLCN gene, which functions as a tumor suppressor and plays a critical role in regulating cell growth and collagen synthesis." (PMID 40723533, 2025). "FLCN-deficient cells then lose homeostatic balance and become metabolically challenged, likely the main driver of tumour growth." (PMID 40426219, 2025). "The Birt–Hogg–Dubé (BHD) syndrome is a rare, autosomal dominant disorder caused by germline mutations in the FLCN gene, which encodes a tumor suppressor protein." (PMID 40630489, 2025). "FLCN, located on chromosome 17p11.2, encodes the folliculin protein, a tumor suppressor that regulates key cellular processes, including mTOR and AMPK signaling pathways, which control cell proliferation, metabolism, autophagy, and mitochondrial function." (PMID 40277780, 2025). "Taken together, these findings underscore the role of FLCN as a tumor suppressor in the liver, particularly in male mice, where the loss of FLCN leads to a more aggressive tumor phenotype." (PMID 40189703, 2025). "flcn-1 is the C. elegans ortholog of the human FLCN gene, which encodes the tumor suppressor Folliculin that plays an evolutionarily conserved role in regulating glycogen storage." (PMID 39913540, 2025). "The dual inactivation of FNIP1/2 in mouse kidneys leads to polycystic kidney enlargement akin to FLCN deficiency, highlighting their roles as tumor suppressors, as mice with FNIP1 and/or FNIP2 knockouts exhibit tumors in multiple organs." (PMID 40143966, 2025). "This activation of ISRE-associated genes is mediated by the increased expression of STAT1 and STAT2, providing insight into the paradoxical decrease in cellular proliferation following FLCN tumor suppressor loss." (PMID 39201746, 2024). "As BHD-associated RCCs arise upon loss of the wild-type (WT) FLCN allele, usually due to a somatic second hit, folliculin functions as a tumor suppressor in the kidney." (PMID 36440963, 2023). "Folliculin (FLCN) is a tumor suppressor causing the Birt–Hogg–Dubé syndrome and is involved in energy homeostasis regulation by controlling several metabolic pathways." (PMID 35328408, 2022). "He further showed that FLCN loss in luminal subtypes promotes tumor growth through TFE3 activation and subsequent induction of glycolysis and angiogenesis, which are controlled by activation of the PGC-1α/HIF-1α pathway." (PMID 35070081, 2022). "In tumor cell lines, the loss of FLCN resulted in slower endocytic trafficking of EGFR by decreased Rab7A GTP-to-GDP turnover, resulting in prolonged and elevated phosphorylated EGFR and downstream signaling." (PMID 35863698, 2022). "Significant advances have been made during the past five years towards the tumor suppressor function of FLCN and its association with BHD syndrome." (PMID 35070081, 2022). "In other report, activation of this pathway was associated with tumor growth in a kidney-specific FLCN-deficient mouse model." (PMID 33981707, 2021).
tumor (continued). "As a tumor suppressor, FLCN loss induces a polycystic phenotype in the kidney and the development of cystic renal cell carcinoma." (PMID 33981707, 2021). "Folliculin was characterized as a tumor suppressor, and loss-of-function mutations were identified as the cause of the phenotypic features associated with BHD syndrome." (PMID 33981707, 2021). "For example, in the context of Birt–Hogg–Dube (BHD) syndrome both PGC-1α and the tumor suppressor FLCN are altered resulting in predisposition to patients developing lung cysts, hair follicle tumors, and renal cancer." (PMID 33022986, 2020). "Here, we show that genetic deficiency of Folliculin, a tumor suppressor, leads to misconnection of blood and lymphatic vessels in mice and humans." (PMID 33298956, 2020). "Birt–Hogg–Dubé syndrome is caused by inactivating the mutations of FLCN, a tumor suppressor gene which encodes folliculin." (PMID 32850947, 2020). "The knockdown of FLCN caused HIF2α to enter the nucleus in advance, further exacerbating the aggressive behavior of tumor." (PMID 32850947, 2020). "Most mutations affecting FLCN result in the truncation of the protein, and therefore loss of its associated functions, as typical for a tumor suppressor." (PMID 32195250, 2020). "In vitro experimental evidence has shown that most of the FLCN missense/in-frame mutations impaired folliculin tumor suppressor function by disrupting the stability of the protein." (PMID 31615547, 2019). "We further demonstrate that FNIP1 and Tsc1 are capable of compensating for each other in the chaperoning of mutated FLCN tumor suppressor." (PMID 29774133, 2018). "Folliculin (FLCN) is known for its role as a tumor suppressor and also has been implicated in metabolic reprogramming of adipose tissue." (PMID 28677104, 2018). "Rab7A WT, FLCN WT or the tumour-associated FLCN K508R mutant were purified from transfected 293T cells." (PMID 28656962, 2017). "Folliculin is thought to function as a tumor suppressor that is associated with the mammalian target of rapamycin (mTOR) pathway." (PMID 28151982, 2017). "The expression of phosphorylated ERK (pERK) and S6 (pS6), which are downstream in the pEGFR signalling cascade, was also higher in the FLCN−/− and tumour-associated mutant cells than in the cells expressing FLCN WT." (PMID 28656962, 2017). "The model proposed by these studies predicts that loss-of-FLCN function would lead to suppression of mTORC1 function; such a model contradicts the role of FLCN as a tumour suppressor." (PMID 28656962, 2017). "FLCN WT significantly increased the GTPase activity of Rab7A compared to the GST vector alone, and there was a trend towards decreased GTPase activity of the tumour-associated mutant form of FLCN (FLCN C9)." (PMID 28656962, 2017). "The gene associated with BHD encodes the protein folliculin (FLCN) which acts as a tumour suppressor and interacts with mTOR and AMPK signalling pathways." (PMID 26603437, 2016). "The characterization of FLCN as a positive amino acid-induced stimulator of TORC1 activity opens new avenues for research into how the loss of FLCN function results in the tumor formation typical of those affected by Birt–Hogg–Dubé syndrome." (PMID 27462445, 2016). "Together, these findings indicate that BHD patients possibly bear mutant FLCN-associated neoplasms, while preserving the wild-type allele." (PMID 26974543, 2016). "BHD syndrome is caused by mutations of the FLCN gene, which codes a protein called folliculin and functions as a tumor suppressor gene." (PMID 27871249, 2016). "The present somatic mutation analysis of FLCN revealed that five of the six adenocarcinoma/MPH-like neoplasms had LOH, and that the wild-type copy of FLCN was preserved in all lesions with LOH." (PMID 26974543, 2016). "In this study, we demonstrated that mTOR inhibitor, sirolimus, is able to suppress FLCN-deficient allograft and xenograft tumor growth." (PMID 26418749, 2015).
tumor (continued). "The mutated gene for BHD encodes the protein folliculin (FLCN) which acts as a tumour suppressor and interacts with mTOR and AMPK signalling pathways." (PMID 24772173, 2014). "Testing FLCN species (such as tumor-associated mutants and phosphomutants) in the cell cycle progression assay we present here is an additional, significantly faster method, to differentiate between putative mutant forms and polymorphisms." (PMID 23874397, 2013). "The biologic significance of this observation is supported by the findings that cells expressing tumor-associated FLCN mutants fail to exhibit a delay cell cycle progression." (PMID 23874397, 2013). "Mutations in the FLCN gene associated with kidney tumorigenesis fail to slow cell cycle progression, suggesting a link between cell cycle progression and the tumor suppressor function of FLCN." (PMID 23874397, 2013). "All of the tumor-associated mutants fail to delay cell cycle progression through the S and G2/M phases, suggesting a genetic link between FLCN's tumor suppressor function and its ability to control cell cycle progression." (PMID 23874397, 2013). "Most cancer-causing mutations lead to a carboxy-terminal truncation of folliculin, pointing to a functional importance of this domain in tumour suppression." (PMID 22977732, 2012). "UOK257-H255R cells expressed a low level of FLCN protein resulting in loss of tumor suppressor function and deregulation of TGF-β signaling, even though they expressed slightly more FLCN mRNA than UOK257-4 cells." (PMID 20573232, 2010). "Loss of FLCN expression across various tumor types is also associated with increased nuclear mitochondrial gene expression." (PMID 21162720, 2010). "Such FLCN‐mutated tumours are invariably indolent and show benign behaviour." (PMID 41384711, 2026). "Thus, FLCN‐mutated tumours with ‘hybrids’ features also show mutually exclusive IHC features, with variable combinations of CD117 (KIT) reactive eosinophilic cells, and CK7 positive clear cells, likely owing to their different cells of origin." (PMID 41384711, 2026). "Such atypical FLCN‐mutated tumours exhibit diverse morphologies and additional molecular alterations (for example, a concomitant TFEB gain/amplification), and typically lack the mosaic (‘hybrid’) cell morphology and IHC profiles seen in the typical FLCN‐mutated tumours." (PMID 41384711, 2026). "Similarly, folliculin (encoded by FLCN) is a tumor suppressor implicated in Birt–Hogg–Dubé syndrome." (PMID 40981152, 2025). "Given that the FLCN mutation, a tumor suppressor of the mTOR pathway, is central to the pathogenesis of BHDS, inhibiting this pathway could potentially decrease the risk of tumor recurrence after transplantation." (PMID 40740168, 2025). "The FLCN gene, a known tumor suppressor, encodes the folliculin protein, comprising 14 exons." (PMID 40988748, 2025). "FLCN mutations disrupt cellular homeostasis by impairing mitochondrial biogenesis and metabolism, leading to diverse histologic and clinical phenotypes depending on the tumor type and context." (PMID 40277780, 2025). "FLCN mutations may contribute to tumorigenesis in the lungs, and smoking could accelerate tumor development in BHD patients." (PMID 40630489, 2025). "The gene is a tumor suppressor gene that encodes the follicle-stimulating hormone folliculin." (PMID 41305765, 2025). "Additionally, cDC1s from FlcnΔDC mice bearing MC38 tumours had the largest number of differentially expressed genes, indicating a pronounced effect of FLCN deficiency on cDC1s in the TME." (PMID 37407815, 2023). "Some tumours are associated with Birt-Hogg-Dubé (BHD) syndrome harbouring FLCN germline mutations." (PMID 36816543, 2023). "Notably, similar to FLCN deficiency, SLC38A2 deficiency in DCs eliminates the anti-tumour effect of glutamine supplementation, thereby establishing this glutamine transporter and FLCN signalling as critical drivers of cDC1 function and tumour immunity." (PMID 37407815, 2023).
tumor (continued). "FLCN is a tumor suppressor gene on chromosome 17, which encodes the folliculin protein." (PMID 37273290, 2023). ",9,37, 38, 39, 40 Taken together, BHD-associated renal tumourigenesis may be largely attributed to the exclusive loss of FLCN as the main tumour driver." (PMID 37182269, 2023). "A selective growth-inhibitory effect of Mithramycin A has been observed in FLCN-deficient tumor cells as well,which are characterized by activated wild-type TFE3, suggesting that TFE3-driven tumor cells may be specifically sensitive to this drug." (PMID 37095531, 2023). "FLCN encodes a protein known as folliculin, which is believed to act as a tumor suppressor, based on Knudson’s two-hit hypothesis, in BHDS-associated renal tumors." (PMID 37490463, 2023). "The ISRE gene activation program is directed by upregulate STAT1 and STAT2 and may explain why loss of the FLCN tumor suppressor, paradoxically, reduces cellular proliferation." (PMID 33459596, 2021). "The upregulated IFN signature could thus explain why loss of the FLCN tumor suppressor, paradoxically, represses cellular proliferation." (PMID 33459596, 2021). "FLCN is a tumor suppressor gene that encodes for the protein folliculin." (PMID 33670168, 2021). "Accordingly, we reasoned that perhaps the tumor suppressor function of some FLCN variants could be restored upon lowering the temperature." (PMID 33137092, 2020). "Folliculin (FLCN) gene mutations that may be tumour suppressive are suspected to be causative of this syndrome." (PMID 32190329, 2020). "As a putative tumor suppressor, the vast majority of reported FLCN mutations are truncating mutations including nonsenses, frameshifts, splice site mutations and large deletions/duplications, which will result in truncated protein or absent of mRNA by nonsense-mediated decay." (PMID 31615547, 2019). "In addition to FLCN germline mutation, a second somatic mutation in the remaining FLCN allele has been found in tumour cells." (PMID 30326848, 2018). "However, if FLCN activates mTORC1 signalling at the lysosome, then loss-of-FLCN function would lead to suppression of mTORC1, which seems to contradict FLCN’s role as a tumour suppressor protein." (PMID 28656962, 2017). "To ensure that the GAP activity of FLCN is not due to co-purification of other mammalian proteins, we GST-purified FLCN WT protein, or a tumour-associated mutant form of FLCN (FLCN C9) from bacteria and tested their ability to hydrolyse GTP when combined with Rab7A." (PMID 28656962, 2017). "Birt-Hogg-Dubé (BHD) syndrome is a rare inherited autosomal genodermatosis and caused by germline mutation of the folliculin (FLCN) gene, a tumor suppressor gene of which protein product is involved in mechanistic target of rapamycin (mTOR) signaling pathway regulating cell growth and metabolism." (PMID 27871249, 2016). "Precisely how loss-of-function mutations in FLCN lead to tumor development requires further investigation, although it is possible that cells attempt to compensate for the reduction in FLCN-mediated mTORC1 activation by amplifying the activity of other mTORC1 activators or growth-promoting pathways." (PMID 27462445, 2016). "Moreover, we further developed a xenograft tumor mouse model by inoculating human FLCN-deficient UOK 257-1 cells." (PMID 26418749, 2015). "To determine whether sirolimus can also exert suppression on human FLCN-deficient tumor growth, we developed a xenograft tumor mouse model for testing by inoculating human FLCN-deficient UOK 257-1 cells that were isolated from the original UOK 257 line." (PMID 26418749, 2015). "Our results demonstrated that sirolimus could effectively inhibit Flcn-deficient allograft tumor growth, suggesting that mTOR inhibitors may be effective in treating FLCN-deficient RCC." (PMID 26418749, 2015). "Herein, we treated these allograft and xenograft mouse models with the mTOR inhibitor, sirolimus, and demonstrated that sirolimus could efficiently suppress FLCN-deficient tumor growth." (PMID 26418749, 2015).